IL10 (interleukin 10)
Diseases named in the same sentence as IL10 in open-access papers (continued):
Sharing a sentence is not in itself a finding about the gene and the disease.
co-infection (continued). "In co-infection with B. malayi and M. tuberculosis, the decreased function of DCs and macrophages to migrate and present antigens to T cells results in decreased expression of cytokines such as IL-10, IFNα, and IFNγ." (PMID 33193291, 2020). "It has been shown that COX2 can be induced by S. mansoni to downregulate IL-10-dependent host immune responses in the skin of mice; co-infection resulted in higher COX2 expression which potentially down-regulates immune responses in the liver, thus activating the liver damage pathway." (PMID 32111243, 2020). "However, dengue virus type-2 co-infection can negatively modulate the intracellular growth of L. amazonensis and prevent the expression of IFNβ and IL-10 in macrophages when compared to macrophages infected with L. amazonensis only." (PMID 33193291, 2020). "aeruginosa co-infection showed a marked increase in IL-10-producing tolerogenic DCs." (PMID 32425944, 2020). "In addition to a higher percentage of IL-10–expressing Tregs in coinfected lungs, IL-10 producers also showed significantly higher median fluorescence intensity (MFI) for IL-10 on day 6 after IAV (co)infection suggesting higher IL-10 production per cell." (PMID 30998505, 2019). "IL10 is thus an obvious candidate to test in our co-infection model." (PMID 29881380, 2018). "Co-infection with different helminths may counteract the IL-10 effect and the distinct cytokine response profiles generated may be used to define immunity as well as the severity of the resultant disease." (PMID 29970128, 2018). "Importantly, in this study, we provide the first evidence of IL-27 mediated regulation of IFNγ and IL-10 during human CMV infection in the setting of HIV co-infection." (PMID 28338007, 2017). "In addition, we reported in vitro data showing that HIV-1 infection of macrophages attenuates IL10 responses to co-infection with Mtb, leading to exaggerated inflammation." (PMID 26986567, 2016). "In co-infected mice, neutralization of IL-10 reduced bacterial loads in both the liver and in the blood, suggesting a contribution of this cytokine to the increased systemic levels of S. Typhimurium during co-infection." (PMID 24787713, 2014). "We therefore hypothesized that the IL-10-dependent increase in systemic colonization of S. Typhimurium during co-infection could result from an effect of IL-10 on resident macrophages." (PMID 24787713, 2014). "This IL-10 response was attenuated in chronic HCV infection even with HCV/HIV-coinfection." (PMID 18554409, 2008). "Interestingly, the co-infection group showed a higher IL-2/IL-10 and IFN-γ/IL-10 ratios, indicating a more pronounced effort to activate T-cells and macrophages and an overreaction might potentially provoke a collateral damage." (PMID 40014608, 2025). "Furthermore, another study revealed that HIV-TB co-infection weakens immune defenses due to high IL-10 secretion and PD1 expression, leading to poor antigen presentation, which may explain the higher TB mortality in co-infected individuals." (PMID 40546529, 2025). "In conclusion, the results presented herein indicated that HTLV/HCV co-infection was associated with a trend to IFN-γ production while HCV-infected individuals presented a positive correlation between both inflammatory cytokines (IL-8 and IFN-γ) and the regulatory cytokine IL-10." (PMID 33717024, 2021). "The results presented herein indicated that HTLV/HCV co-infection was associated with a trend in IFN-γ production while HCV-infected individuals presented a positive correlation with both inflammatory cytokines (IL-8 and IFN-γ) and the regulatory cytokine IL-10." (PMID 33717024, 2021). "Co-infection of E. maxima with C. perfringens suppressed the expression of IFNα, IFNγ, IL-1β, IL-2, IL-12, IL-13, IL-17, NO, and transforming growth factor-β4 genes, but increased the expression of IL-8, IL-10, IL-15, and lipopolysaccharide-induced TNFα factor." (PMID 33193291, 2020).
co-infection (continued). "Furthermore, SFB monocolonization as well as SFB and MNV co-infection did not cause pathological changes in the gut epithelium of both analyzed Il10−/− mouse strains." (PMID 31396223, 2019). "Retrovirus/Sporothrix co-infection in cats from this study led to important changes in immunological balance, leaning towards an immunosuppressive profile with higher levels of IL-10, which could prevent the activation of a Th1 response that would be favourable against sporotrichosis." (PMID 30500849, 2018). "Therefore, we assume that co-infection with C. sinensis in HBV infection may suppress the immune response by stimulating IL-10 production as well as inhibiting IFN-γ secretion as a result." (PMID 27348302, 2016). "IL-10 may also protect against the development of lung injury during co-infection." (PMID 25651926, 2015). "Thus, IL-10 plays an important role in the modulation of CD4+ Th1 cells in FIL/TB co-infection." (PMID 25211342, 2014). "The results showed that the levels of IL-6, IL-10, IFN-α, and IFN-γ (from 12 hpi to 96 hpi) in the co-infection cells were significantly higher compared to the ALV-J and CIAV mono-infected cells or the controls." (PMID 38674684, 2024). "Peihu Fan’ team discovered that the HP-PRRSV/PCV2 co-infection group had up-regulated serum concentrations of TNF-α and IL-10, while IFN-γ was lower in the co-infection groups, especially the HP-PRRSV/PCV2 group, than in the single-infection groups." (PMID 36992486, 2023). "Consistently, we also found that IL-10 expression was significantly up-regulated by the PRRSV alone and PCV2 and PRRSV co-infection groups, and a stronger effect was observed in PRRSV–PCV2 group." (PMID 36992486, 2023). "Co-infection with filaria, a nematode, parasitizes the lymphatic system and induces IL-10, which prevents the development of ECM, while IL-10 knockout (KO) mice co-infected with filaria developed ECM." (PMID 35632518, 2022). "During a co-infection model with St, where IFN-γ contributes to survival and IFN-γ+ CD4+ T cells do not reach their numerical peak until the third week of infection, IL-10 is detrimental in the second week of infection." (PMID 35631044, 2022). "Overall, the results showed upregulation of cytokines IL-10, IFN-γ, and IL-6 and downregulation of IL-12p70, Il-2, and TNF-α during severe Babesia co-infection in mice." (PMID 35719355, 2022). "Co-infection tended to promote inflammation with heightened IFN-γ and IL-1β and diminished IL-10 levels when compared to monoinfections." (PMID 36389843, 2022). "Compared with the group infected with GTPV alone, the expressions of IL-1β, IL-6, IL-10, and IFN-α in the co-infection groups were inhibited." (PMID 33827620, 2021). "Studies using MAH-infected BMDCs stimulated with LPS, which mimicked co-infection conditions, lead to the production of high levels of TLR-mediated IL-10 alongside reduced IL-12 levels." (PMID 32425944, 2020). "In summary, HBV-infected patients had a unique biomarker clustering profile comprising IFN-γ, IL12p70, IL-10, IL-6, and TNF-α that was distinct from the profile of the healthy controls and from those with HBV/HIV coinfection." (PMID 30815625, 2019). "Various effects of in vivo co-infection of T. gondii and E. tenella in chickens were observed on IFN-γ, TNF-α, IL-10 and IL-12." (PMID 30081942, 2018). "This is in accordance with another study showing that T. muris evoked an increase in pro-inflammatory cytokines such as TNF-α along with an increase of IL-4 and IL-10 compared to BCG infection and co-infection." (PMID 28192437, 2017). "The level of IL-10 was statistically higher in smoking patients, in patients infected with EBV, HPV as well as in EBV-HPV co-infection." (PMID 27547238, 2016).
co-infection (continued). "Overall we could observe a tendency for reduced levels of IFN-γ, TNF, IL-6, and IL-10 in the serum of co-infected groups, when compared to P. yoelii 17XNL single infected group, suggesting a modulation of P. yoelii 17XNL induced immune response by Leishmania co-infection." (PMID 27446022, 2016). "Our results indicate that Dolabelladienetriol significantly inhibits Leishmania in macrophages even in the presence of factors that exacerbate parasite growth, such as IL-10, TGF-β and HIV-1 co-infection." (PMID 22970332, 2012). "The co-infection with H3N2 SwIV and either SW114 or Nagasaki induced higher levels of IL-1β, TNF-α, IL-6, IL-12 and IL-10 compared to mock or H3N2 SwIV infection alone." (PMID 23157617, 2012). "An independent t-test was utilized to determine the comparison of serum IL-10 and IL-6 levels, while a Mann-Whitney test was used to establish the comparison of serum leptin levels in leprosy patients with and without helminth co-infection." (PMID 41239264, 2025). "This study aimed to measure the serum levels of IL-10, IL-6, and leptin in leprosy patients with and without helminth co-infections." (PMID 41239264, 2025). "Clinically, late presentation was associated with coinfection rate; polysymptomatology; high IFN-ɣ, IL-6 and IL-10 levels; nonresponse to antiretroviral therapy; and virological failure- and tuberculosis coinfection-motivated changes to therapy." (PMID 38992229, 2024). "Additionally, co-infection of pigs with NADC30-like PRRSV-2 strain SDlz1601 and S. suis upregulated IL-1β, IL-6, IL-8, TNF-α, CCL4, IL-10, and INF-β in PAMs." (PMID 38547254, 2024). "A significant difference was revealed in the levels of TNF-α, IL-12, and IL-10 among the patient groups without infection, with latent infection/co-infection, active single, double and triple co-infection." (PMID 36653846, 2023). "Significantly higher level of IL-10 is observed in patients with active double co-infection compared to patients without infection and with latent infection/co-infection (p = 0.029 and p = 0.0035, respectively)." (PMID 36653846, 2023). "Upon re-stimulation of lymph node cells with H1 in vitro, the antigen-specific production of IFNγ, IL-17, or IL-10 was not affected by N. brasiliensis co-infection." (PMID 36753434, 2023). "To examine whether co-infection alters the induction patterns of cytokines and chemokines, we measured the serum levels of IP-10, MCP-1, TNF-α, IL-1-β, IL-6, IL-10, and IFN-γ over the course of infection using ELISA." (PMID 34711897, 2021). "In parallel, a slight induction of IL-10 was measured in the lungs of more pigs from the PRRSV/swIAV group, than from the single-infected group, as already observed by others after PRRSV/swIAV co-infection." (PMID 34834975, 2021). "The revealed reduced production of IL-4 and IL-10 indicates that despite the fact that patients with HIV/TB co-infection were in the late stages of the disease, they did not have a shift towards the expression of Th2 class cytokines." (PMID 34835417, 2021). "Patients with bacteremia had significantly lower IL-10 concentrations (p=0.02) compared to those with malaria parasitemia with or without bacteremia co-infection." (PMID 34177883, 2021). "While our results indicated that HO-1 inhibition with Sn PP failed to improve immunity to either Lm or Sp co-infections, we did see a reduction in Sp bacterial burdens in co-infected mice treated with anti-IL-10 (blocking) antibody." (PMID 32714882, 2020). "Moreover, IL-10-producing tolerogenic DCs were remarkably induced by MAH and P. aeruginosa co-infection." (PMID 31440223, 2019). "However, the co-infection between Plasmodium vivax and enteroparasitoses increased levels of TNF-α, and IL-10 in comparison to those with single malarial infection." (PMID 29293589, 2018).
co-infection (continued). "Activation of IL-10 occurred following Mtb infection and was further increased due to co-infection, although this effect of co-infection failed to reach significance (p = 0.07) due to variability among animals." (PMID 26908312, 2016). "Those with Plasmodium mono-infection had higher levels of IL-4, IL-6, IL-10, IL-12, IL-13, IL-17A, IFN-γ, and MIP1-α/CCL3 compared with DENV mono-infection or co-infection; those with Plasmodium mono-infection had more cough than those with DENV mono-infection." (PMID 27128316, 2016). "Finally, we demonstrate that for the filarial co-infections at least, this diminished frequency of multifunctional CD4+ T cell responses was partially dependent on IL-10 as IL-10 blockade significantly increased the frequencies of CD4+ Th1 cells." (PMID 25211342, 2014). "Another hypothesis in the present study is that regulatory responses, including Tregs, IL-10 and TGF-β, play a role in the immune responses of the vertebrate host during co-infections." (PMID 24670210, 2014). "We previously reported that patients with schistosomiasis and HIV coinfection had significantly lower production of the cytokines IL-4 and IL-10 than schistosome-infected persons who were HIV negative." (PMID 20351784, 2010). "Since mast cells protect Il10−/− mice from spontaneous IBD, their failure to influence the severity of inflammation triggered by exposure of Il10−/− mice to piroxicam or co-infection with H. rodentium and H. typhlonius may seem paradoxical at first glance." (PMID 20808919, 2010). "This demonstrates a propensity for HCV-induced IL-10 production by PBMC from uninfected individuals that is exaggerated by HIV infection and attenuated by chronic HCV infection, even in the setting of HIV coinfection." (PMID 18554409, 2008). "Elevated IL-10 levels have been proposed as markers of disease activity in syphilis, particularly among people living with HIV who may display altered immune regulation due to co-infection." (PMID 40529360, 2025). "Additionally, DosR-specific IL-10 production by CD8+ T cells was strongly and negatively correlated with activation on naïve CD4+ T cells (r = −0.6730, p = 0.0006), indicative of a suppressive milieu accompanying HLTBI co-infection." (PMID 41148837, 2025). "However, in both groups of patients with HIV/TB co-infection, that indicator was significantly decreased (on average by 14.8 times, p < 0.0001), and again there was no statistical difference in IL-10 production." (PMID 38790916, 2024). "Besides, significantly decreased semen levels of IL-6 and IL-1β were detected in HR-HPV patients regardless of the presence of coinfections, while significantly reduced levels of IL-10 were only detected in HR-HPV+Coinf- patients." (PMID 39258253, 2024). "In addition, ME/CFS patients with active triple co-infection have a higher level of IL-10 in comparison to patients without infection, with latent infection/co-infection and active single infection (p = 0.0107, p = 0.0034 and p = 0.0321, respectively)." (PMID 36653846, 2023). "The IL-10/TNF-α ratio was on average 30-fold (69.9 [12.5–140.7]), 10-fold (19.7 [1.6–115.2]), 6-fold (13.0 [3.5–24.9]) and 8-fold (16.9 [2.4–86.6]) higher in those with single or P. falciparum co-infections with filariae, STH and intestinal protozoa, respectively, than in uninfected participants." (PMID 35421083, 2022). "However, expression of IL-10 and IFN-γ mRNA was unaltered upon co-infection." (PMID 35140712, 2021). "To examine the immune profile of individuals with co-infection, we compared the concentration of 15 immune markers (IL-1β, IL-6, IL-8, TNF-α, IL-7, G-CSF, MCP-1/CCL2, MIP-1-α/CCL3, IL-12, IFN-γ, IL-13, IL-17A, GM-CSF, IL-10, and TGF-β1) among the three groups using Kruskal-Wallis ANOVA." (PMID 27128316, 2016). "HIV coinfection did not change IL-10, IFN-α, TNF, or IFN-γ presence within excised LNs." (PMID 27462092, 2016).
co-infection (continued). "As opposed to A. lumbricoides and Trichuris trichiura co-infections, we were neither able to detect a positive relationship between hookworm antigen-induced IL-10 secretion and intestinal worminess, nor to detect negative associations between IL-10 and Th1/Th2-type cytokines." (PMID 21909439, 2011). "IL-6, IL-8, and IL-10 levels in CML patients with bacterial and fungal coinfection were higher than those in patients without infection." (PMID 37114211, 2023). "Among patients with HAM, IFN-γ/IL-10, and TNF-α/IL-10 ratios were higher in those individuals with active TB than those HAM patients without co-infection." (PMID 35187000, 2022). "Serum concentrations of TNF-α, IL-6, IL-10 and TGF-β1 were measured, separately, in healthy controls and in patients with HIV-HCV coinfection, distributed in two groups, those without and those with liver cirrhosis." (PMID 23840511, 2013). "Similarly, co-infection with PbA and the non-lethal strain PbXAT prevented the development of ECM in C57BL/6 mice, but not in IL-10 KO mice." (PMID 35632518, 2022). "In addition, we show that IL-27 controls IFNγ and mediates IL-10 producing Tr1 cells during CMV infection, with or without co-infection with HIV." (PMID 28338007, 2017). "The effect of 16 hour exposure to HCV proteins on the number of IL-10+ PBMC was quite substantial (5–10 fold increase) in HIV-infected and uninfected control groups, while the increase in HCV-infected individuals, with or without HIV coinfection, was marginal." (PMID 18554409, 2008). "Compared to P. berghei-mono, mice in the co-infection-100c group had significantly lower levels of IFN-γ on days 5 and 8 pi and higher levels of IL-4, IL-5, IL-13 and TGF-β on days 3, 5, and 8 pi, while no significant changes in IL-10 levels were observed between the two groups." (PMID 24670210, 2014).